INS (insulin)
Diseases named in the same sentence as INS in open-access papers (continued):
Sharing a sentence is not in itself a finding about the gene and the disease.
Hyperglycemia (continued). "What has been described so far removes the feedback that insulin and glucagon exert on glucose metabolism, causing an imbalance in favour of hyperglycemia that further catalyzes the abnormalities described as a vicious cycle." (PMID 39768436, 2024). "Kcnk16L114P neonates exhibit loss of glucose-stimulated Ca2+ entry and insulin secretion leading to transient neonatal hyperglycemia and death." (PMID 38700926, 2024). "Insulin regimen-associated differences in hyperglycemia and daily insulin dose persisted after adjusting for covariates." (PMID 38919469, 2024). "Previous studies have demonstrated that XBP1‐deficient mice exhibited moderate hyperglycemia and glucose intolerance, with reduced insulin secretion originating from β‐cells." (PMID 38967361, 2024). "Elimination of insulin-producing cells with streptozotocin (STZ) also induces hyperglycemia in rodents, but significant weight loss ensues despite over-eating." (PMID 38596458, 2024). "Safety assessments indicated that LNCsClo administration mitigated Clo-associated metabolic side effects, such as hyperglycemia, insulin imbalance, and liver enzyme alterations." (PMID 39598541, 2024). "Managing hyperglycemia with chemical drugs or insulin causes numerous complications, including insulin‐induced fatty liver." (PMID 38726423, 2024). "Type 1 diabetes (T1D)-associated hyperglycemia develops, in part, from loss of insulin-secreting beta cells." (PMID 38781241, 2024). "The autoimmune mechanism in T1DM causes gradual loss of pancreatic β-cell, which progresses to hyperglycemia and ultimate reliance on consistent insulin therapy." (PMID 38952492, 2024). "Type 1 diabetes (T1D) is an autoimmune disease characterized by hyperglycemia due to the loss of insulin-producing β-cells, primarily driven by T-cell-mediated pancreatic islet inflammation." (PMID 39451194, 2024). "In T2DM, hyperglycemia leads to the dysregulation of insulin-mediated glucose homeostasis in insulin-susceptible tissues, for example, myocytes and adipose tissue." (PMID 38474775, 2024). "Pheochromocytoma often causes hyperglycemia by secreting catecholamines, which induce gluconeogenesis in the liver and inhibit pancreatic insulin secretion through the alpha‐2 adrenergic receptor." (PMID 39498182, 2024). "The external IAS refers to hyperinsulinemia, positive insulin antibodies, hyperglycemia, and hypoglycemia caused by the use of insulin." (PMID 39575003, 2024). "Consistent with the present study, previous studies have shown that AO causes a disturbance in glucose metabolism by decreasing insulin secretion, resulting in hyperglycemia post-stroke, thereby exacerbating stroke outcomes." (PMID 39063072, 2024). "Prolonged hyperglycemia is the first and more obvious consequence of the delay in initiating basal insulin, with an increased risk for micro- and macrovascular outcomes and all-cause mortality, likely independently from other conventional risk factors." (PMID 38441838, 2024). "These mutations can affect the production and secretion of insulin, resulting in inadequate insulin levels and subsequent hyperglycemia." (PMID 38673052, 2024). "Hyperglycemia is a hallmark of DM, characterized by impaired insulin action or decreased insulin secretion." (PMID 39429274, 2024). "KEGG pathway analysis revealed that Cluster2 was primarily enriched in biological processes related to adherens junctions, long-term potentiation, and insulin signaling pathways, which are associated with post-burn hyperglycemia." (PMID 38410514, 2024). "EMCV is a picornavirus which has been shown to infect and cause necrosis in pancreatic β cells, inducing insulin-dependent hyperglycemia in mice and hamsters." (PMID 38444587, 2024). "GSK3β deactivation also counteracts the adverse pharmacological toxicity of hyperglycemia and insulin feedback caused by PI3K inhibition." (PMID 38755637, 2024).
Hyperglycemia (continued). "This is because TP patients suffer from deficiencies in insulin, glucagon, amylin, and pancreatic polypeptide, and as a result, they will often develop hyperglycemia due to increased hepatic gluconeogenesis leading to decreased hepatic insulin sensitivity." (PMID 38792534, 2024). "In cases of symptomatic hyperglycemia with weight loss, polydipsia, polyuria, or severe hyperglycemia with ketonuria, insulin is the preferred initial treatment." (PMID 38559691, 2024). "It is distinguished by absolute or relative deficits in insulin production (T1D) and/or (T2D), which are linked to persistent hyperglycemia and abnormalities in the metabolism of proteins, lipids, and carbohydrates." (PMID 39170696, 2024). "Several studies have shown that hyperglycemia and elevated insulin levels, which can cause neuronal damage and death, thus affecting brain function, are important factors leading to cognitive deficits in diabetes." (PMID 39200168, 2024). "It is also well-known that elderly patients are at a higher risk of suffering from deleterious consequences of hyperglycemia, such as a life-threatening hyperosmolar state which requires aggressive hydration and insulin therapy." (PMID 38632533, 2024). "Another study revealed that more weight gain than what is recommended during pregnancy is associated with a greater decrease in insulin sensitivity between 15 and 35 weeks of gestation, which can lead to maternal and foetal hyperglycaemia." (PMID 38778289, 2024). "It is characterized by the gradual destruction of pancreatic beta‐cells, resulting in a complete deficiency of insulin and hyperglycemia." (PMID 39365284, 2024). "An 80% reduction in basal insulin at the onset of EXE helps mitigate hyperglycemia after EXE more effectively than basal insulin suspension and appears to be associated with a reduced risk of hypoglycemia during and after the activity." (PMID 38542818, 2024). "New-onset hyperglycemia due to PD-1 inhibitors is difficult to discern from variations in blood sugar due to other causes such as insulin resistance." (PMID 39130825, 2024). "T2DM, marked by the progressive loss of insulin secretion by pancreatic β-cells within the context of peripheral insulin resistance, leads to glucose intolerance and hyperglycemia." (PMID 38435190, 2024). "Introducing insulin as a choice for patients with uncontrolled hyperglycemia (HbA1C≥9) has been questionably associated with cardiovascular sequelae." (PMID 39295783, 2024). "Eating a high-fat diet to generate insulin resistancewhile injecting low-dose STZ can cause hyperglycemia." (PMID 38712836, 2024). "A single dose of dexamethasone has been identified as a risk factor for hyperglycemia because it can stimulate gluconeogenesis and inhibit peripheral insulin action." (PMID 38951764, 2024). "Atg‐deficient mice revealed hypoinsulinemia and hyperglycaemia, as autophagy regulates intracellular insulin content." (PMID 39656379, 2024). "In Type 1 diabetes (T1D), hyperglycemia is a result of autoimmune destruction of pancreatic beta cells leading to an absolute deficiency of insulin secretion." (PMID 38985787, 2024). "Through the application of APN-mRNA-LNP, we successfully increased the direct production of insulin, boosted the uptake of glucose into cells, and decreased inflammation associated with uncontrolled hyperglycemia." (PMID 38916734, 2024). "It is characterized by hyperglycemia, a condition involving a high blood glucose level brought on by deficiencies in insulin secretion, decreased activity of insulin, or both." (PMID 38837635, 2024). "One of the consequences of hyperglycemia and the associated heightened demand for insulin production and secretion in T2D is thought to be the development of endoplasmic reticulum (ER) stress in pancreatic beta-cells." (PMID 38797835, 2024).
Hyperglycemia (continued). "Consistent with the central role of mitochondria in coupling glucose metabolism to insulin secretion, mitochondrial abnormalities in pancreatic β-cells have been shown to cause defective insulin secretion and hyperglycemia." (PMID 38485716, 2024). "In particular, vascular dysfunction caused by dyslipidemia, adipose tissue remodeling, insulin metabolism dysfunction, and hyperglycemia leads to hypertension." (PMID 38892574, 2024). "Among the top altered pathways identified, most were directly associated with DM and hyperglycemia phenotypes, such as insulin secretion signaling pathways." (PMID 38187339, 2024). "One of the causes of diabetic cardiomyopathy (DCM) is apoptosis, caused by hyperglycemia and abnormal disorder in plasma glucose and insulin level." (PMID 37274326, 2023). "Whenever patients require artificial feeding, the enteral route, if not contraindicated, should be used, since parenteral nutrition is associated with a higher frequency of hyperglycemia and greater insulin requirements." (PMID 37836433, 2023). "Maternal hyperglycemia led to a higher risk of macrosomia, the need for blue light therapy and higher umbilical cord blood C-peptide and insulin concentrations compared to babies born from normal glycemic mothers." (PMID 36767469, 2023). "OxS can also contribute to beta-cell dysfunction and reduced glucose-induced insulin secretion, thereby further increasing the risk of hyperglycemia and T2D progression." (PMID 37371869, 2023). "T2DM is characterized by faulty insulin secretion or deficiency and defective metabolism of carbohydrates and lipids in tissues, leading to an increase in postprandial hyperglycemia levels." (PMID 37138848, 2023). "Summary of key studies evaluating insulin secretion as a potential mechanism contributing to TS-associated hyperglycemia in." (PMID 36875465, 2023). "An early correction of hyperglycaemia with insulin infusion was associated with lower mortality as compared with a delayed management of blood glucose level." (PMID 37330419, 2023). "In patients with T2DM, insulin cannot regulate glycogen synthesis or glucose production, leading to increased hepatic gluconeogenesis as the main cause of hyperglycemia in T2DM." (PMID 38138997, 2023). "STZ administration, as one of chemically induced type 1 diabetes models relates to the destruction of the pancreatic beta cells leading to deficiency in insulin production, hyperglycemia, and weight loss." (PMID 37851320, 2023). "Administration of intravascular streptozotocin and injection of streptozotocin monohydrate can cause a reduction in insulin levels and lead to hyperglycemia within a short period, as reported in previous studies." (PMID 38026676, 2023). "DM is a complex metabolic condition characterized by chronic hyperglycemia and disruptions in carbohydrate, lipid, and protein metabolism caused by flaws in insulin secretion, action, or both." (PMID 37375806, 2023). "In HFD-fed mice, NAC improved insulin sensitivity, an effect that prevents compensatory hypertrophy of islets and resulting hyperglycemia and avoids HFD-induced loss of beta-cell identity." (PMID 37237860, 2023). "These caused wrongful glucagon administration and hyperglycemia, which was followed by increased insulin supply when the augmentation was resolved." (PMID 36755913, 2023). "In particular, the suppression of the transportation of glucose from the extracellular compartment to the intracellular compartment due to insulin resistance leads to a reduction in the synthesis of muscle glycogen and glycolysis, causing hyperglycaemia." (PMID 37107955, 2023). "Hyperglycemia causes reactive oxygen species (ROS)-mediated glucose toxicity in pancreatic β-cells that impairs their insulin-producing function, leading to insulin insufficiency." (PMID 37755075, 2023).
Hyperglycemia (continued). "Uncontrolled hyperglycemia is associated with worse outcomes in COVID-19, making it crucial to achieve optimal glycemic control, which occasionally requires IV insulin therapy." (PMID 37456416, 2023). "Hyperglycemia is caused by insufficient secretion of insulin and its biological function is impaired." (PMID 36873938, 2023). "They utilize continuous glucose monitoring data and AI to predict and adjust insulin doses, reducing the risk of hypoglycemia and hyperglycemia." (PMID 38161783, 2023). "Third, we excluded patients with previous CV diseases, including HF; at-risk patients with highly uncontrolled hyperglycemia, such as insulin use or type 1 DM; and at-risk patients with vulnerability, such as metastatic cancers." (PMID 38066029, 2023). "Our study confirmed that BS intervention can increase insulin sensitivity and improve the hyperglycemia caused by HFD." (PMID 37048203, 2023). "It seems that the overexpression of miR-147b inhibits beta cells to decrease blood insulin causing hyperglycemia." (PMID 37786444, 2023). "The present study has several drawbacks, such as the use of a streptozotocin-induced type 1 diabetes model, which causes a decrease in endogenous insulin synthesis followed by the development of hyperglycemia and weight loss." (PMID 37893048, 2023). "An alternative that also reduces the risk of hypoglycemia during exercise is suspending basal insulin during exercise, as shown in our study, but it has a higher risk of hyperglycemia after the exercise." (PMID 36964201, 2023). "The purported mechanisms causing hyperglycemia rely on the imbalance between insulin action and insulin secretion, and are primarily instigated by inflammation, cytokine action, neuroendocrine mechanisms, and counter-regulatory hormones." (PMID 36895277, 2023). "Advanced age leads to the aging of pancreatic β-cells, resulting in defective insulin secretion and decreased glucose sensitivity; hyperglycemia is a risk factor for atherosclerosis." (PMID 36875469, 2023). "Treatment of PN-related hyperglycemia with insulin in turn predisposes patients to hypoglycemia, which likewise predicts death and poorer clinical outcomes." (PMID 37674887, 2023). "The increased glucose variability in diabetic patients and those treated by insulin was expected and consistent with the significant association to a higher rate of hyperglycaemias in the linear mixed models." (PMID 37330419, 2023). "Insufficient insulin secretion and diminished tissue responses to insulin can coexist in the same patient, making it often unclear which abnormality, if any, is the primary cause of hyperglycemia." (PMID 37510145, 2023). "The current findings strongly indicate that brain insulin resistance leading to long-lasting hyperglycemia causes neural damage and thus increases the risk of developing MCI and AD." (PMID 36834741, 2023). "Endoplasmic reticulum stress is generated when high levels of insulin are required, such as due to hyperglycemia, which causes the protein to become misfolded." (PMID 37745252, 2023). "STZ causes pancreatic β-cell damage and reduces the amount of insulin secreted, which results in hyperglycemia." (PMID 38046568, 2023). "DM is a WM disease name, referring to a chronic metabolic disorder characterized by hyperglycemia and caused by absolute or relative insufficient secretion of insulin and/or IR, which is classified into the pre-DM, DM, and DM chronic complication stages." (PMID 37349778, 2023). "T1D is a chronic autoimmune disease characterized by the destruction of insulin-producing β-cells in the pancreas, causing hyperglycemia and requiring the use of exogenous insulin." (PMID 36602848, 2023). "IR is deeply associated with the progression of T2DM, which limits insulin’s ability to facilitate glucose uptake and promotes lipid accumulation, ultimately resulting in hyperglycemia." (PMID 37764646, 2023).
Hyperglycemia (continued). "Alloxan is reduced to form diluric acid by binding with the SH sugar-binding site of glucokinase, an enzyme which is essential for glucose-induced insulin secretion causing hyperglycemia." (PMID 37143509, 2023). "The high frequency of hyperglycemia during the luteal phase was associated with lower insulin sensitivity in the early to mid and late luteal phase compared to the early follicular phase in women with T1D (n = 12)." (PMID 36833469, 2023). "In this regard, it should be noted that both hyperglycemia and hypoglycemia, including those induced by insulin therapy, are associated with a poor prognosis of ischemia." (PMID 36834685, 2023). "Typically, defects in glucose-sensing machinery are associated with impaired insulin secretion and hyperglycemia." (PMID 36837926, 2023). "O304 stimulated glucose uptake and utilization in skeletal muscle in vivo under insulin deficient conditions and mitigated hyperglycemia associated glycogen accumulation in skeletal muscle and heart." (PMID 37626210, 2023). "In our study, long-acting insulin, despite being prescribed at higher doses, was associated with more hyperglycaemias but similar mean blood glucose compared with patients under other types of insulin." (PMID 37330419, 2023). "Hyperglycemia associated with keto-acidosis was obscured due to self-administered insulin corrections just prior to presentation (recorded blood glucose on admission of 7.8 mmol/L)." (PMID 38047210, 2023). "Insulin deficiency leads to hyperglycemia, which requires the administration of exogenous insulin to prevent life-threatening acute and chronic complications." (PMID 37887145, 2023). "Our findings revealed that LETZ-induced PCOS in mice caused elevation in FBG and insulin levels, suggesting IR and hyperglycemia (HG), two vital features of metabolic abnormalities." (PMID 36979879, 2023). "It consists of a dysfunction of the pancreatic β-cells, which induce a significant deficiency of insulin and consequent hyperglycemia." (PMID 36976069, 2023). "This did not coincide with previous studies showing that chronic restraint stress (CRS) is linked to hyperglycaemia and unaltered levels of insulin in rats." (PMID 36814911, 2023). "Chronic hyperglycemia and hyperinsulinemia can lead to uncontrolled insulin signaling, which can cause the multiplication and survival of pancreatic cells by activating various signaling pathways." (PMID 37842365, 2023). "In mitochondrial diabetes, ATP deficiency occurs, which inhibits insulin secretion and results in hyperglycemia." (PMID 37370930, 2023). "In line with previous studies, the cause of hyperglycemia in animals was due to the interaction between the growth and expansion of triglyceride generated by the deficit of insulin levels." (PMID 37959677, 2023). "IR in the liver is caused by impaired insulin metabolism influencing glucose metabolism and enhancing insulin-mediated lipogenesis to cause hyperglycemia." (PMID 37208737, 2023). "Insulin, used as a treatment to prevent hyperglycaemia, has also been associated with adverse neurodevelopmental outcomes, but this association was made using a much lower treatment threshold and target mean blood glucose than described in this study." (PMID 38004135, 2023). "In adults with T2D, HbA1c > 9%, and signs or symptoms of hyperglycemia (polyuria, polydipsia, weight loss), insulin-based therapy IS RECOMMENDED to improve glycemic control." (PMID 37468901, 2023). "Oxidative stress and hyperglycemia in metabolic diseases lead to adverse neurophysiological phenomena, including neuronal loss, synaptic dysfunction, and improper insulin signaling, resulting in PD." (PMID 38124101, 2023). "By providing continuous real-time glucose data and automated insulin delivery, wearable insulin biosensors have the potential to improve glycemic control and reduce the risk of hypoglycemia and hyperglycemia." (PMID 38239544, 2023).